RNU6-1107P (RNA, U6 small nuclear 1107, pseudogene)
Gene: Small nuclear RNA gene on chromosome 11 (113,859,346 to 113,859,449, forward strand). Ensembl gene ENSG00000201687.
Homologues: Orthologues: chimpanzee U6 (100% identical), macaque U6 (90% identical), mouse Gm23038 (85% identical), guinea pig U6 (80% identical), pig U6 (75% identical). Paralogues in human: RNU6-842P (88% identical), RNU6-1011P (88% identical), RNU6-1117P (88% identical), RNU6-38P (88% identical), RNU6-1124P (87% identical), RNU6-28P (87% identical), RNU6-338P (87% identical), RNU6-810P (87% identical), RNU6-1029P (86% identical), RNU6-1094P (86% identical), RNU6-1296P (86% identical), RNU6-12P (86% identical), and 1284 more.